CEBPB (CCAAT enhancer binding protein beta)
Diseases named in the same sentence as CEBPB in open-access papers (continued):
Sharing a sentence is not in itself a finding about the gene and the disease.
anaplastic large cell lymphoma (10 papers, 2013 to 2024). Anaplastic large cell lymphoma (ALCL) is a rare and aggressive peripheral T-cell non-Hodgkin lymphoma, belonging to the group of CD30-positive lymphoproliferative disorders, which affects lymph nodes and extranodal sites. "CEBPB was described to have a pro-oncogenic role also in other HMs, such as anaplastic large cell lymphoma (ALCL) as well as in different cancers, e.g., breast, colon, kidney, stomach, prostate, and ovaries." (PMID 39769352, 2024). "It was found that CEBPB and BCL2A1 can induce cell transformation and increase the survival of anaplastic large cell lymphomas cells." (PMID 37626099, 2023).
COVID-19 (10 papers, 2022 to 2025). A disease caused by infection with severe acute respiratory syndrome coronavirus 2. "The COVID-19 GWAS risk allele on chromosome 3p21.31 (rs17713054) creates a CEBPB (CCAAT enhancer binding protein beta) motif resulting in an enhancer that directly interacts with the LZTFL1 (leucine zipper transcription factor like 1) promoter." (PMID 35648852, 2022). "Comparing the COVID-19-specific HEP7 cells to the closely related HEP6 cells, shows an inverse CEBPA/CEBPB ratio, demonstrating a metabolic vs. acute phase regulation expression program." (PMID 40087773, 2025). "In agreement with previous studies, we also highlighted the elevation of ATF3, CEBPB, FOSL2, and MITF with COVID-19 severity." (PMID 39712003, 2024). "In contrast, severe COVID-19 cases exhibited activation of CEBPD in peripheral immune cells, while CEBPB was exclusively activated in respiratory epithelial cells." (PMID 37936693, 2023). "In the other datasets, CEBPB increased in the patients with Kawasaki and CoV2-MyoC, and CEBPD increased in the patients with COVID-19 and Kawasaki." (PMID 36225942, 2022). "A decrease in the expression of the following genes was also observed in COVID-19-positive patients: RAPGEF1 (p = 0.0091), MAP2K1 (p = 0.038), CEBPB (p = 3.3 × 10−6), STAT6 (p = 0.041), JUN (p = 1.4 × 10−8), PRKACA (p = 0.021), and AKT1 (p = 1.3 × 10−6)." (PMID 36298734, 2022). "Classical monocytes in the patient with acute stage of BNT162b2-myocarditis were similar to those in the patients with COVID-19 in terms of decreased level of JUN/FOS expression and increased regulon activity of CEBPB." (PMID 36225942, 2022).
Hepatic steatosis (10 papers, 2014 to 2025). Steatosis is a term used to denote lipid accumulation within hepatocytes. "Empagliflozin treatment prevents liver fibrosis as well as hepatic steatosis, and metformin reduces protein levels of the cancer marker CD133 through the AMPK-CCAAT/enhancer-binding protein beta (CEBPβ) signaling pathway." (PMID 37436535, 2023).
lymphoma (10 papers, 2017 to 2025). A malignant (clonal) proliferation of B- lymphocytes or T- lymphocytes which involves the lymph nodes, bone marrow and/or extranodal sites. "MYC is linked to apoptosis and lymphoma whereas ZEB1 and CEBPB are enhancer binding proteins." (PMID 28765546, 2017).
triple-negative breast carcinoma (10 papers, 2018 to 2025). An invasive breast carcinoma which is negative for expression of estrogen receptor (ER), progesterone receptor (PR), and human epidermal growth factor receptor 2 (HER2). "Aerobic glycolysis, a hallmark of cancer, can regulate MDSC immunosuppression and tumor immunity via a specific CEBPB isoform in triple-negative breast cancer." (PMID 39830505, 2024). "CEBPB pathways affected MDSCs and maintained tumor immunosuppression in triple-negative breast cancer." (PMID 35493068, 2022). "Among REST, CTCF, and CEBPB, CEBPB is the only member that was significantly enriched in C19MChigh group (REST and CTCF data were not shown) and hence we investigated whether CEBPB is functional in triple negative breast cancers." (PMID 30335837, 2018).
colitis (9 papers, 2019 to 2025). Inflammation of the colon. "In this study, we aimed to investigate the role of CEBPB in the progression of cancers associated with colitis." (PMID 40487290, 2025). "Previous studies have also reported that exhibits a therapeutic effect in experimental colitis by inhibiting the CEBPB/PCK1 and CEBPB/EFNA1 pathways, which are associated with the PI3K-Akt and P38 MAPK pathways." (PMID 38675921, 2024). "In conclusion, we found that PCK1 and EFNA1 are highly expressed in colitis and they are regulated by CEBPB through two super-enhancers, and we further demonstrate their role in vivo and in vitro." (PMID 35910380, 2022). "In LPS-induced Caco-2 cells, drugs commonly used in clinical colitis including tofacitinib, oxalazine, mesalazine, and sulfasalazine inhibited mRNA levels of CEBPB, PCK1, and EFNA1." (PMID 35910380, 2022). "To verify whether CEBPB regulates PCK1 and EFNA1 to improve colitis, we designed the interfering RNA of CEBPB." (PMID 35910380, 2022). "In summary, this study shows that inhibition of super-enhancer–driven CEBPB/PCK1 and CEBPB/EFNA1 signaling pathways can reduce LPS-induced barrier dysfunction in vitro and improve DSS-induced experimental colitis in vivo." (PMID 35910380, 2022). "In vivo experiments, nintedanib significantly alleviated DSS-induced colitis in mice by inhibiting CEBPB/PCK1 and CEBPB/EFNA1 signaling pathways." (PMID 35910380, 2022).
multiple myeloma (9 papers, 2007 to 2024). "CEBPB, which showed gains in four OAML, functions as transcription factor in myeloid cells, but it also has a pathogenetic role in multiple myelomas, and positively regulates BCL2 in B cells." (PMID 32316399, 2020).
non-small cell lung carcinoma (9 papers, 2012 to 2024). A group of at least three distinct histological types of lung cancer, including non-small cell squamous cell carcinoma, adenocarcinoma, and large cell carcinoma. "CEBPB is required for Nrf2-mediated drug resistance in Nrf2-activated non-small cell lung cancer cells." (PMID 37958656, 2023). "The result from another study proved that one isoform of CEBPB could directly induce PD-L1 transcription when non-small cell lung cancer lines were treated with metformin." (PMID 38007473, 2023). "The transcriptional activator NRF2 is frequently activated in non-small cell lung cancer, and NRF2 overexpression results in the accumulation of CCAAT Enhancer Binding Protein Beta (CEBPB)." (PMID 38135679, 2023). "Here, the authors show that NRF2 cooperates with CEBPB and remodels enhancers to confer tumor-initiating activity on NRF2- activated non-small cell lung cancers." (PMID 33219226, 2020). "Previously, we published that IL-1β induces MMP gene expression in non-small cell lung carcinoma and chondrosarcoma cells, and that IL-1β induction of MMP gene expression in these cancer lines is dependent on the transcriptional activity of the CEBPβ." (PMID 23342250, 2012).
pancreatic cancer (9 papers, 2019 to 2025). "Exosomes from pancreatic cancer cells reduced myosin heavy chain (MHC) expression by activating the P38/CEBPβ/UBR2/Atrogin1 signaling pathway in skeletal muscle cells, leading to muscular duct atrophy and muscle weight loss in the cachexia model of mice with in situ pancreatic cancer." (PMID 38689293, 2024). "Interestingly, the analysis identified enrichment of multiple TFs including TCF4, WT1, CEBPD, CEBPB, SUZ12, and ZFP281 across all stages of pancreatic cancer progression." (PMID 30644396, 2019).
psoriasis (9 papers, 2014 to 2025). An autoimmune condition characterized by red, well-delineated plaques with silvery scales that are usually on the extensor surfaces and scalp. "STAT3, CEBPB, and NF-κB are recognized as significant biomarkers in the pathogenesis of psoriasis and may serve as potential drug targets for its treatment." (PMID 40487290, 2025). "Comparing core signaling pathways of psoriasis and non-psoriasis and their downstream cellular dysfunctions, STAT3, CEBPB, NF-κB, and FOXO1 are identified as significant biomarkers of pathogenic mechanism and considered as drug targets for the therapeutic treatment of psoriasis." (PMID 37373186, 2023). "In this study, we identified NF-κB, FOXO1, CEBPB, STAT3, and ERK1/2 as the drug targets for the treatment of psoriasis." (PMID 37373186, 2023). "Together with the elevated gene expression of CEBPB, the expression of keratinocyte-terminal differentiation genes, such as IVL, FLG2, and TGM1, is upregulated in the lesional skin of psoriasis." (PMID 32070069, 2020).
nasopharyngeal carcinoma (8 papers, 2022 to 2024). A carcinoma arising from the nasopharyngeal epithelium. "For example, it has been demonstrated that PGC1α binding to CCAAT/enhancer binding protein β (CEBPβ) can induce the upregulation of Cpt1a gene in nasopharyngeal carcinoma cells." (PMID 37524243, 2023). "For example, in the case of nasopharyngeal carcinoma cells, CEBPB binds to PPAR coactivator-1α and promotes the transcription of CPT1A, which ultimately increased the level of fatty acid oxidation." (PMID 36225942, 2022). "CEBPB has been reported to confer radiation resistance in nasopharyngeal carcinoma." (PMID 35459206, 2022). "The PGC1α/CEBPB/CPT1A axis, which enhances lipid β-oxidation, increases ATP and NADPH levels and promotes cellular radiation resistance in nasopharyngeal carcinoma." (PMID 39607749, 2024). "The in vitro experiments demonstrate that the PPAR coactivator-1α (PGC1α) binds to CCAAT/enhancer binding protein β (CEBPB) and increases FAO regulated by CPT1A in nasopharyngeal carcinoma (NPC) cells." (PMID 35216362, 2022). "In nasopharyngeal carcinoma and HNSCC, CEBPB is involved in PGC1α-mediated radiation resistance." (PMID 35459206, 2022). "In another study, PGC-1α, the key transcription coactivator regulating CPT1A and CPT1B, binds to the transcription factor CEBPB to promote CPT1A expression, which enhances FAO activity to maintain the high NADPH/NADP+ ratio, contributing to radiation resistance of nasopharyngeal carcinoma cells." (PMID 35936710, 2022). "PGC-1α PGC1α binds to CCAAT/enhancer binding protein β (CEBPB) to enhance CPT1A transcription, resulting in activation of FAO through PGC1α/CEBPB/CPT1A/FAO signaling axis, which can promote radiation resistance of nasopharyngeal carcinoma (NPC)." (PMID 37033619, 2023).
amyotrophic lateral sclerosis (7 papers, 2013 to 2025). Amyotrophic lateral sclerosis (ALS) is a neurodegenerative disease characterized by progressive muscular paralysis reflecting degeneration of motor neurons in the primary motor cortex, corticospinal tracts, brainstem and spinal cord. "In patients with amyotrophic lateral sclerosis (ALS), CEBPB expression was elevated in lymphocytes and nerve tissue, making it a potential marker for ALS progression." (PMID 41007174, 2025).
Cachexia (7 papers, 2015 to 2022). Severe weight loss, wasting of muscle, loss of appetite, and general debility related to a chronic disease. "We also observed a clear decrease in genes dominantly regulating fat cell differentiation, including CEBPB, CEBPD, BMP2, and KLF4, in vPreA in cachexia group, as compared to patients without cachexia." (PMID 36376273, 2022).
metabolic syndrome (7 papers, 2015 to 2025). A cluster of metabolic risk factors for CARDIOVASCULAR DISEASES and TYPE 2 DIABETES MELLITUS. "Notably, CEBPB is a gene connected to both OA and metabolic syndrome, and it holds diagnostic value for OA individuals with metabolic syndrome." (PMID 41007174, 2025).
osteosarcoma (7 papers, 2009 to 2023). A usually aggressive malignant bone-forming mesenchymal neoplasm, predominantly affecting adolescents and young adults. "Then, we built transcription factor CEBPB recombinant plasmid and transfected it to osteosarcoma cell line MG‐63." (PMID 31364785, 2019). "CEBPB can inhibit the proliferation of osteosarcoma via regulating the expression of CLEC5A." (PMID 31364785, 2019).
viral infection (7 papers, 2011 to 2025). "This suggests a potential role of CEBPB in modulating immune responses in the context of severe viral infection." (PMID 40918096, 2025). "Interestingly, transcriptional regulation of CEBPB and CEBPD in humans and macaques, but not mouse cells stimulated with double-stranded RNA, which mimics a viral infection, were also observed in an independent data set." (PMID 31637998, 2019).
heart failure (6 papers, 2019 to 2025). Inability of the heart to pump blood at an adequate rate to meet tissue metabolic requirements. "The mice downregulated of CEBPB has been reported to display substantial resistance to cardiac failure upon pressure overload, indicating its repression of cardiomyocyte growth and proliferation in the adult mammalian heart." (PMID 31772688, 2019). "In a further attempt to obtain functional evidence supporting the proposed mechanisms responsible for MAPK7 regulation of CEBPβ signaling, we carried out rescue experiments on Mapk7-cko mice to evaluate whether overexpression of CEBPβ could prevent MAPK7 ablation-induced heart failure post-MI." (PMID 32223896, 2020). "Although CEBPB failed to enter the range of important CSA signature genes in our study, its role in the development of heart failure cannot be ignored." (PMID 37234159, 2023).
Hyperglycemia (6 papers, 2015 to 2022). An increased concentration of glucose in the blood. "Moreover, CEBPB mRNA was increased in MetS patients, and a tendency to increased values was observed in individuals with hyperglycemia." (PMID 33540559, 2021). "Reduced IGF-1 expression in DRG was also observed in the pre-diabetic HFD mouse model, suggesting hyperglycemia per se was not a sole trigger of reduced CEBPβ function." (PMID 35298717, 2022). "Hyperglycemia-induced activation of PKC and/or suppression of CaMKII and calcineurin might therefore contribute to impaired activity and binding of NFAT1 and CEBPβ to target the Igf1 gene promoter." (PMID 35298717, 2022).
myeloid leukemia (6 papers, 2013 to 2024). A clonal proliferation of myeloid cells and their precursors in the bone marrow, peripheral blood, and spleen. "The CEBPB gene has already been described as a vitamin D target in myeloid leukemia cells." (PMID 32325790, 2020). "As this step marks the transition to an acute leukemia, the overlapping genes (CEBPB, FOS, FOSB, IL8, S100A12, SOCS2) might be involved in the aggressiveness of MLL-AF9 myeloid leukemia blasts." (PMID 24517546, 2014).
cervical cancer (5 papers, 2017 to 2024). A primary or metastatic malignant neoplasm involving the cervix. "On the other hand, overexpression of MIR503 host gene regulated invasion and proliferation of cervical cancer cells and accelerated cell apoptosis by miR‐191/CEBPB axis." (PMID 37056778, 2023).
endometriosis (5 papers, 2012 to 2025). The growth of functional endometrial tissue in anatomic sites outside the uterine body. "The results indicated that 13 TFs were identified in both SLE and endometriosis, and 6 of them (EP300, TCF12, CTCF, POLR2A, CEBPB and NFIC) can act on four potential co-diagnostic genes simultaneously." (PMID 39744159, 2025).
Hypertension (5 papers, 2013 to 2026). The presence of chronic increased pressure in the systemic arterial system. "Elucidating the novel role of POU2F2 and CEBPB can assist our understanding of the pathogenesis of hypertension and supports the development of future treatments for hypertension." (PMID 36942826, 2023). "In conclusion, the novel regulation of POU2F2 and CEBPB in VSMCs will help us understand the pathogenesis of hypertension and support the development of future treatments for hypertension." (PMID 36942826, 2023). "In this context, the additive effect of POU2F2 and CEBPB may be able to explain the progressive increase in BP during the development of hypertension." (PMID 36942826, 2023). "‘Unknown I’ contained a diverse set of key driver genes such as SGK1, SIK1 and SLC10A6 (sodium metabolism and hypertension), MT2A and TSC22D3 (glucocorticoid signaling), GADD45G, ERRFI1, GPRC5A, and EGFR (cell growth and apoptosis), and CEBPB, CEBPD, and KCNA5 (heart development and function)." (PMID 25033284, 2014).
osteoarthritis (5 papers, 2009 to 2025). A noninflammatory degenerative joint disease occurring chiefly in older persons, characterized by degeneration of the articular cartilage, hypertrophy of bone at the margins and changes in the synovial membrane. "This study is the first to systematically construct a miRNA–mRNA regulatory network centered on CX3CR1 and CEBPB, identifying several miRNAs previously unreported in the context of osteoarthritis (OA)." (PMID 41007174, 2025).
acute kidney injury (4 papers, 2022 to 2023). Sudden and sustained deterioration of the kidney function characterized by decreased glomerular filtration rate, increased serum creatinine or oliguria. "CEBPB has been reported to promote microRNA-16 expression, resulting in aggravated ischemia/reperfusion-induced acute kidney injury." (PMID 37828427, 2023). "Recent key studies have identified that NLRP3-mediated pyroptosis was activated by CEBPB, which contributed to the promotion of acute kidney injury." (PMID 36248187, 2022).
adenoma (4 papers, 2011 to 2024). A neoplasm arising from the epithelium. "SMAD3, SMAD4, and CEBPB came up as key transcription factors regulating cancer progression at the late adenoma stage." (PMID 36499586, 2022). "Interestingly, three stemness/differentiation-related genes, including LRRC34, CEBPB, and TBX3, showed significant changes in their expression levels in adenoma compared to normal colon mucosa." (PMID 38670944, 2024).
Autoimmunity (4 papers, 2015 to 2020). The occurrence of an immune reaction against the organism's own cells or tissues. "Transcriptome group 3 (ACVRL1, CD93, CEBPB, NINJ1, SRGN) encodes preferentially for proteins related to autoimmunity." (PMID 32325790, 2020). "Because macrophages lacking CEBPB do not remove apoptotic debris very well, such debris may accumulate and contribute to kidney-specific autoimmunity and autoantibody production." (PMID 26629350, 2015).
brain tumors (4 papers, 2014 to 2025). "Another interesting function of CEBPB is its role in the occurrence of mesenchymal phenotype in brain tumors where it is a synergistic initiator of mesenchymal transformation with STAT3." (PMID 24597747, 2014).
esophageal cancer (4 papers, 2013 to 2025). A primary or metastatic malignant neoplasm involving the esophagus. "Only two transcription factors, ATF2 and CCAAT/enhancer-binding protein beta (CEBPB), have not yet been described in oesophageal cancer." (PMID 23800081, 2013).
esophageal squamous cell carcinoma (4 papers, 2015 to 2024). Esophageal squamous cell carcinoma (ESCC) is a type of esophageal carcinoma (EC) that can affect any part of the esophagus, but is usually located in the upper or middle third. "KDM6B promotes the proliferation and migration of esophageal squamous cell carcinoma by increasing the transcriptional activity of CEBPB." (PMID 38710698, 2024).
liver cirrhosis (4 papers, 2007 to 2025). "Some of the important hub genes in the BisoGenet-derived PPI for liver cirrhosis and HCC diseases were E2F1, TAL1, CEBPB, ELF1, RAD21, CEBPB, and MYC." (PMID 35265561, 2022).